NRAD1 (non-coding RNA in the aldehyde dehydrogenase 1A pathway)
Synonyms: formerly NCRNA00284; LINC00284
Gene: Long non-coding RNA gene on chromosome 13 (43,908,669 to 44,042,929, forward strand). Ensembl gene ENSG00000233725.
Diseases named in the same sentence as NRAD1 in open-access papers:
NRAD1 is named in the same sentence as 14 diseases in open-access papers, as found by Europe PMC text mining. Sharing a sentence is not in itself a finding about the gene and the disease. The quoted sentences say what the papers report.
breast carcinoma (8 papers, 2020 to 2023). "In the case of LINC00284, also known as non-coding RNA in the aldehyde dehydrogenase 1 A pathway (NRAD1), it is upregulated in ovarian and breast cancer cells and also involved in angiogenesis in ovarian cancer cells." (PMID 35740273, 2022). "Consistent with the breast cancer patient tumor data, NRAD1 is predominately expressed in basal-like breast cancer cell lines (e.g., SUM149 and MDA-MB-468) and is lowly expressed in cell lines of other subtypes (e.g., ER+ MCF7 cells), and normal tissues." (PMID 31197235, 2020). "NRAD1 may be a cause of at least some of the stemness and tumorigenicity associated with ALDH1A3 in breast cancer, as its knockdown reduced tumor growth and mammosphere formation potential." (PMID 36672441, 2023). "Importantly, this association went beyond the three manipulated cell lines, as NRAD1 levels correlated with ALDH1A3 in breast cancer patient tumors and in a panel of breast cancer cell lines." (PMID 31197235, 2020). "The striking enrichment of NRAD1 in basal-like breast cancer and TNBC suggests that NRAD1 may serve as an attractive diagnostic or prognostic target." (PMID 32244924, 2020). "In breast cancer for example, lncRNAs nuclear paraspeckle assembly transcript 1 (NEAT1), metastasis-associated lung adenocarcinoma transcript 1 (MALAT1), and non-coding RNA in the aldehyde dehydrogenase 1A pathway (NRAD1), have all been described as oncogenic and dysregulated in breast cancer." (PMID 34072264, 2021). "ALDH1A3 and RA induce lncRNA non-coding RNA in the aldehyde dehydrogenase 1A pathway (NRAD1), formerly known as LINC00284 in breast cancer." (PMID 36672441, 2023). "This revealed that two of the seven CSC-lncRNAs, NRAD1/LINC00284 and DANCR, are significantly enriched in TNBC/basal-like breast cancers." (PMID 32244924, 2020). "Among the lncRNAs, NRAD1 and DANCR were significantly associated with higher hazard ratios in basal-like breast cancers but not TNBC patients." (PMID 32244924, 2020). "Future experiments will reveal if NRAD1 chromatin binding alters chromatin structure and the full importance of NRAD1 in gene regulation, particularly with respect to TNBC/basal-like breast cancers and CSCs where it is most abundant and contributes to cancer cell survival and tumor growth." (PMID 31197235, 2020). "In breast cancer patient tumor samples and in a panel of cell lines, LINC00162 levels did correlate with ALDH1A3 mRNA; however, to a decreased degree than NRAD1." (PMID 31197235, 2020). "The results with MCF7 cells suggest that growth inhibition from reducing NRAD1 is not exclusive to TN basal-like breast cancers; however, based on the apoptosis results, targeting the lncRNA seems less effective in the ER + MCF7 cells with lower levels of NRAD1 expression." (PMID 31197235, 2020).
asthma (1 paper, 2022). "Furthermore, the enriched pathways of NRAD1 and LPAR4 included immune system pathways, such as those related to complement and coagulation cascades, asthma, and autoimmune thyroid disease." (PMID 36465614, 2022).
preeclampsia (1 paper, 2022). Preeclampsia is a hypertensive disorder of pregnancy that is characterized by new-onset hypertension with proteinuria presenting after 20 weeks of gestation, and depending on mild or severe forms may initially present with severe headache, visual disturbances, and hyperreflexia. "The qRT-PCR results indicated that LOC101927355, LINC00551, PART1, and NRAD1 were downregulated in the preeclampsia placenta samples (p = 0.009, p = 0.012, p = 0.004, p = 0.001, respectively) compared to the control placentas." (PMID 35740273, 2022). "Six lncRNAs were validated and differentially expressed (p < 0.05) in the preeclampsia and control placentas: UCA1 and HCG4 were found upregulated, and LOC101927355, LINC00551, PART1, and NRAD1 downregulated." (PMID 35740273, 2022). "The present study uncovered the downregulation of LOC101927355, LINC00551, PART1, and NRAD1 and the upregulation of HCG4 in the preeclampsia placentas." (PMID 35740273, 2022).
tumor (8 papers, 2020 to 2023). "NRAD1/LINC00284 has since been implicated as a crucial regulator of gene expression and tumor progression through sponging various miRNAs in multiple cancers." (PMID 36672441, 2023). "Targeting NRAD1 with antisense oligonucleotides decreased cell viability and reduced tumor growth of TNBC cells lines in a patient-derived xenograft (PDX)." (PMID 31197235, 2020). "Together, these data demonstrate that targeting NRAD1 reduced the tumor growth of established TNBC tumors, and the number of cells with CSC-like characteristics within these tumors." (PMID 31197235, 2020). "Anti-NRAD1 GapmeR treatment significantly reduced the rate of tumor growth in all three TNBC models." (PMID 31197235, 2020). "Given the co-expression of NRAD1 with CSC marker ALDH1A3 in the Aldefluorhigh cells and the role of ALDH1A3 in gene expression regulation and tumor progression, we wondered if NRAD1 is regulated by ALDH1A3." (PMID 31197235, 2020). "The smaller anti-NRAD1-treated tumors possessed more dead tumor cells, consistent with the observed effect on apoptosis when NRAD1 is silenced in vitro." (PMID 31197235, 2020). "Targeting NRAD1 in TNBC tumors using antisense oligonucleotides reduced cell survival, tumor growth, and the number of cells with CSC characteristics." (PMID 31197235, 2020). "Finally, NRAD1 is a novel downstream target of aldehyde dehydrogenase 1A3 (ALDH1A3) and the first lncRNA described to contribute to gene expression changes induced by this CSC marker and mediator of tumor progression." (PMID 31197235, 2020).
cancer (5 papers, 2020 to 2021). A tumor composed of atypical neoplastic, often pleomorphic cells that invade other tissues. "Our screening of lncRNAs led to the identification of TNBC/basal-like/CSC-enriched NRAD1 as a new mediator of cell survival within these tumors and cancer cells." (PMID 31197235, 2020). "This is consistent with the decreased cell viability and reduced spheroid-potential of cancer cells post knockdown of NRAD1." (PMID 31197235, 2020). "Together, these data suggest that NRAD1 inhibition is detrimental to both cancer cells and stem-like cells with spheroid-forming potential." (PMID 31197235, 2020).
NRAD1 also shares sentences with these, for which no sentence is quoted: ovarian carcinoma (4 papers); colorectal cancer (2); gastric cancer (2); autoimmune thyroid disease (1); hepatocellular carcinoma (1); lung carcinoma (1); papillary thyroid carcinoma (1); serous ovarian carcinoma (1); triple-negative breast carcinoma (1).